KLF13 (KLF transcription factor 13)
Diseases named in the same sentence as KLF13 in open-access papers (continued):
Sharing a sentence is not in itself a finding about the gene and the disease.
endometriosis (2 papers, 2015 to 2023). The growth of functional endometrial tissue in anatomic sites outside the uterine body. "Given that endometriosis predisposes patients to cancers of the female reproductive tract, we first summarize the current state of knowledge on the involvement of KLF9 and KLF13 in this condition." (PMID 38067370, 2023). "Finally, KLF13-null lesions contribute to defective steroid hormone receptor signaling in the pathology of endometriosis, and KLF15 negatively regulates E2-induced epithelial cell proliferation, which is associated with endometriosis and endometrial cancer." (PMID 26223982, 2015). "KLF13 transcript levels also were of lower abundance in eutopic endometrium of women with endometriosis when compared to non-diseased tissue." (PMID 38067370, 2023). "Interestingly, KLF13-null lesions had no alterations in activity or readout in the Notch or Hedgehog signaling pathways when compared to corresponding wildtype lesions, indicating that KLF13 had less involvement than KLF9 in the pathogenesis of endometriosis." (PMID 38067370, 2023).
esophageal cancer (2 papers, 2025). A primary or metastatic malignant neoplasm involving the esophagus. "The specific role of KLF13 is context dependent and complex; it can act as a tumor suppressor in GC via the β-catenin pathway, whereas a recent study identified KLF13 as a pro-tumorigenic factor in esophageal cancer." (PMID 41438085, 2025).
Holt-Oram syndrome (2 papers, 2020 to 2023). Holt-Oram syndrome (HOS) is the most common form of heart-hand syndrome and is characterized by skeletal abnormalities of the upper limbs and mild-to-severe congenital cardiac defects. "Holt–Oram syndrome has been typically associated with mutations in TBX5, even though new evidence has shown that KLF-13 plays a pathogenic role, as researchers have identified KLF-13 as a genetic modifier for TBX5." (PMID 36836777, 2023).
Insulin resistance (2 papers, 2017 to 2024). Increased resistance towards insulin, that is, diminished effectiveness of insulin in reducing blood glucose levels. "Knockout (KO) mouse study of KLF13 showed that activated T lymphocytes from KO mice had decreased expression of chemokine RANTES which has been implicated in many inflammatory diseases, including insulin resistance and obesity." (PMID 28508896, 2017).
lung carcinoma (2 papers, 2023 to 2024). "In this matter, TGFBR2 has recently been proposed as a tumor suppressor with prognostic value in early-stage NSCLC; however, there is no prior evidence of an association between KLF13 and lung cancer prognosis, so further research is required." (PMID 36900258, 2023). "In addition to KLF1, KLF13, KLF14 and KLF16 or KLF18 (?)with machine learning prediction waiting for verification, many KLFs have been found to be associated with the progress of lung cancer by activating or inhibiting target gene expression." (PMID 38560274, 2024). "However, up to now, whether some KLFs (KLF1, KLF13, KLF14 and KLF16) with unknown functions are involved in the progressions of lung cancer have not been fully understood, and remain to be explored or verified at the levels of cell, tissue and animal models." (PMID 38560274, 2024).
microdeletion syndrome (2 papers, 2016 to 2022). "Actually, there are many evidences indicating that KLF13 is associated with some non-neoplastic diseases such as microdeletion syndrome, cardiac abnormality, HPV productive life cycle, adipocyte differentiation, pulmonary fibrosis, non-alcoholic fatty liver disease." (PMID 36336731, 2022).
schizophrenia (2 papers, 2016 to 2022). A major psychotic disorder characterized by abnormalities in the perception or expression of reality. "As expected, the binding motif (ACGCCC) of transcription factor KLF13 does not show enrichment in any group of the risk genes, supporting that over-representation of the GC-box containing genes within the schizophrenia-risk genes or DD/ID-risk genes is not a random effect." (PMID 34750502, 2022).
acute myocardial infarction (1 paper, 2019). Necrosis of the myocardium, as a result of interruption of the blood supply to the area. "Cardiomyocytes overexpressing miR-125b-5p have increased prosurvival signaling and protected the heart from acute myocardial infarction by repressing pro-apoptotic bak1 and klf13." (PMID 30717412, 2019).
and Lobular Carcinoma (1 paper, 2022). "Only Finak Breast Statistics found that KLF3/6/11/16 was highly expressed in invasive breast carcinoma stroma, while KLF13 was higher in Invasive Ductal and Lobular Carcinoma." (PMID 35033064, 2022).
attention deficit and hyperactivity disorder (1 paper, 2024). "Within this context, the objective of the current manuscript is to highlight the potential implications of a genetic variant found within KLF13 in a patient showing neurodevelopmental and psychiatric symptoms encompassing attention deficit and hyperactivity disorder (ADHD)." (PMID 39202416, 2024).
Cachexia (1 paper, 2022). Severe weight loss, wasting of muscle, loss of appetite, and general debility related to a chronic disease. "In our cachexia mouse model, several of the DE genes enriched in the bulk analysis belong to the top-induced genes in oligodendrocytes, such as Mt1, Sgk1, Klf13, and Ptgds, indicating an important role for oligodendrocytes in the pathology of cachexia." (PMID 35031523, 2022).
COVID-19 (1 paper, 2025). A disease caused by infection with severe acute respiratory syndrome coronavirus 2. "For other loci, KLF13 (Kruppel-like factor 13) shows low activity in moderate COVID-19 cases and higher activity in severe cases." (PMID 40650217, 2025).
developmental delay (1 paper, 2020). "The most interesting genes that were damaged by the BCTs are: EPHA6 (the first case with an optic phenotype in humans), UBR3 (the second case with developmental delay in humans), KLF13 (second case with developmental delay in humans)." (PMID 32344861, 2020). "In particular, our results suggest novel candidate genes for retinal degeneration with anophthalmia (EPHA6), developmental delay with speech impairment (KLF13), and developmental delay with brain dysembryoplastic neuroepithelial tumor (UBR3)." (PMID 32344861, 2020).
ischemic stroke (1 paper, 2025). A stroke disorder caused by obstruction of blood flow to the brain, due to thrombotic (local blood clot formation) or embolic (due to a blood clot or other material traveling from another site) event. "Furthermore, core transcriptional regulatory circuitries involving SOX8, FOXK1, and KLF13 were identified, highlighting their roles in the modulation of SE-mediated gene regulation by acupuncture in the ischemic stroke context." (PMID 40109665, 2025). "Our findings suggest that core transcription factors such as SOX8, KLF13, and FOXK1 may serve as crucial therapeutic targets for electroacupuncture in ischemic stroke." (PMID 40109665, 2025).
lung adenocarcinoma (1 paper, 2025). A carcinoma that arises from the lung and is characterized by the presence of malignant glandular epithelial cells. "For lung adenocarcinoma, KLF13 induced ferroptosis via repressing transcription of GPX4, thus sensitizing lung adenocarcinoma cells to chemotherapy drugs." (PMID 41410190, 2025). "The other work documented that KLF13 restrained epithelial–mesenchymal transition of lung adenocarcinoma cells through inhibiting TROAP transcription." (PMID 41410190, 2025). "Our GEPIA database analysis revealed reduced KLF13 levels in lung squamous cell carcinoma (LUSC) and lung adenocarcinoma (LUAD)." (PMID 41410190, 2025).
muscle atrophy (1 paper, 2024). The loss of muscle tissue due to inactivity or disease. "Next, we examined the function of KLF13 in muscle atrophy using a DEX‐induced muscle atrophy mouse model." (PMID 38973459, 2024). "First, we investigated changes in endogenous KLF13 expression in several muscle atrophy mouse models to determine if KLF13 is directly involved in the pathogenesis." (PMID 38973459, 2024). "KLF13 expression was downregulated in several muscle atrophy mouse models, including diabetic, DEX‐treated and cisplatin‐induced models, suggesting that KLF13 may be a convergence point for catabolic signalling across different muscle atrophy stimuli and might contribute to muscle atrophy diseases." (PMID 38973459, 2024). "Furthermore, the mRNA levels of ubiquitin ligases [e.g., Atrogin‐1, muscle ubiquitin ligase of SCF complex in atrophy‐1 (i.e., MUSA1) and F‐box protein 31 (i.e., Fbxo31)], which are known to induce muscle atrophy, were increased in the DEX‐treated cells, and KLF13 knockout augmented these effects." (PMID 38973459, 2024).
myeloma (1 paper, 2021). "Six TFs (CXXC1, BPTF, MAZ, KLF13, CBFB and RFX5) were identified as showing higher connectivity in all myeloma subgroups compared to ND PC, thus exemplifying the process of existing TF ‘re-wiring’ in MM." (PMID 34521827, 2021).
oesophagal cancer (1 paper, 2025). "Nevertheless, the role of KLF13 in oesophagal cancer (EC) remain elusive." (PMID 40450000, 2025).
oral squamous cell carcinoma (1 paper, 2025). "KLF13 was first reported as a tumor promoting in 2010 in oral squamous cell carcinoma." (PMID 40450000, 2025).
sarcopenia (1 paper, 2024). Progressive decline in muscle mass due to aging which results in decreased functional capacity of muscles. "Therefore, this study explored the involvement of KLF13 in sarcopenia to elucidate the underlying molecular mechanisms and suggest novel therapeutic targets for mitigating muscle atrophy and improving the quality of life of individuals with sarcopenia." (PMID 38973459, 2024). "In conclusion, this study highlights the pivotal role of KLF13 as a key regulator of skeletal muscle atrophy by coordinating various sarcopenia triggers." (PMID 38973459, 2024). "These discoveries open the door to potential therapeutic approaches to boost KLF13 expression or activity, which could be a promising treatment option for sarcopenia." (PMID 38973459, 2024).
Sepsis (1 paper, 2024). Sepsis is defined as life-threatening organ dysfunction caused by a dysregulated host response to infection. "Interestingly, KLF13 is a transcription factor in which the induction is associated with an improvement in the symptoms of sepsis-induced myocardial injury in a mouse model." (PMID 39120317, 2024).
small cell lung carcinoma (1 paper, 2021). Small cell lung cancer (SCLC) is a highly aggressive malignant neoplasm, accounting for 10-15% of lung cancer cases, characterized byrapid growth, and early metastasis. "Finally, we show that SMAD3, ZNF217, KLF13, GATA2, GATA3, KLF7, and PHOX2B are components of CRCs in other cancers, including DLBCL, pancreatic, gastric, breast, and small cell lung cancer." (PMID 35201514, 2021).
thyroid cancer (1 paper, 2023). "The relative mRNA level of IFIT1 was significantly increased in siKLF13#1 transfected K1 and TPC1 cells, while greatly decreased in KLF13 overexpressed thyroid cancer cells." (PMID 37817224, 2023). "The expression of KLF13 in thyroid carcinoma and normal tissue was investigated by qPCR and IHC assay." (PMID 37817224, 2023). "Thus, our work demonstrates that the tumor suppressor effect of KLF13 on thyroid carcinoma, which is mediated by regulation of IFIT1 expression through binding to its promoter region." (PMID 37817224, 2023). "The mRNA and protein level of IFIT1 was regulated by KLF13 expression in thyroid carcinoma." (PMID 37817224, 2023). "Compared with normal samples, KLF13 was downregulated in thyroid carcinoma." (PMID 37817224, 2023). "Nevertheless, the exact effect of KLF13 on thyroid carcinoma remained unclear." (PMID 37817224, 2023). "However, the significance of KLF13 in thyroid carcinoma (THCA) is underdetermined." (PMID 37817224, 2023). "In conclusion, KLF13 may function as an anti-tumor protein in THCA by regulating the expression of IFIT1 and offer a theoretical foundation for treating thyroid carcinoma." (PMID 37817224, 2023).
tumor (18 papers, 2020 to 2026). "Treatment with miR‐3126‐5p‐silenced Exos remarkably restrained tumour growth and Ki‐67 expression, which were restored by KLF13 deficiency." (PMID 41410190, 2025). "Clofoctol binds to CSDE1 and enhances its association with KLF13 mRNA -encoding a tumor suppressor- leading to KLF13 mRNA stabilization, reduction of tumor growth and increased mouse survival." (PMID 38600987, 2024). "Further, the co-expression of KLF9 and KLF13 transcripts is evident in the tumor-associated immune cells (e.g., B cells, mast cells, myeloid cells, and T cells), whereas KLF13 mRNA predominates in the tumor-associated plasma cells." (PMID 38067370, 2023). "Furthermore, the elevated glucose consumption and lactate production in tumours of the Exos treatment group were reversed by miR‐3126‐5p deficiency, which were restored by KLF13 knockdown." (PMID 41410190, 2025). "Perhaps this drug or a suitable derivative may eventually provide a gateway to therapeutically induce KLF13 in neoplastic cells and/or tumor-associated immune cells." (PMID 38067370, 2023). "The expression of KLF9 and KLF13 in tumor-associated immune cells and tumor stroma, coupled with the known biology of these proteins in circulating immune cells, makes a strong case for focusing on the functions of these two KLFs in the tumor microenvironment of solid tumors and blood cancers." (PMID 38067370, 2023). "Analysis using Kaplan–Meier plotter demonstrated that high KLF13 mRNA expression showed shorter patient survival and tumor size." (PMID 40450000, 2025). "Recent studies have revealed that KLF13 exhibits dual roles as a tumour suppressor or oncogenic driver across diverse malignancies." (PMID 41410190, 2025). "TAG and FFA concentrations in tumor tissues from the KLF13 + shGPIHBP1 group were markedly lower compare to KLF13 group." (PMID 40450000, 2025). "IHC results showed a positive relation between the expression of GPIHBP1 and KLF13 in tumor samples." (PMID 40450000, 2025). "We found that treatment with Exos significantly facilitated tumour growth, glucose consumption and lactate production in tumours, which were abolished by KLF13 overexpression." (PMID 41410190, 2025). "It is plausible that KLF13, as a tumor suppressor, orchestrates a broader cellular state that is permissive for chemotherapy-induced apoptosis, for instance, by regulating other key pathways like β-catenin." (PMID 41438085, 2025). "Similar to KLF9, KLF13 mRNA and protein levels are significantly lower in prostate tumors than in adjacent non-tumor tissue." (PMID 38067370, 2023). "Previous studies have reported that IFIT1 acts as an oncogene in various tumors, whereas its significance, as well as its involvement in KLF13 suppression of tumor progression, in THCA remains to be determined." (PMID 37817224, 2023). "That KLF13 suppresses cell propagation and migration of THCA cells, we next examined this role of KLF13 in tumor development in vivo using tumor xenograft models." (PMID 37817224, 2023). "Mass spectrometry has identified multiple sites of post-translational modification for KLF9 and KLF13 proteins; however, we know little about the functional relevance of these sites, especially with respect to neoplasia and responses to cancer treatments." (PMID 38067370, 2023). "The results showed that overexpression of KLF13 greatly decreased the tumor size, volume and weight, indicating that KLF13 suppressed the tumor growth of THCA." (PMID 37817224, 2023). "The narrative highlights the alterations (primarily reductions) in KLF9 and KLF13 steady state levels in many different cancers, and their predominant roles as suppressors or promoters of tumor cell growth and migration." (PMID 38067370, 2023). "The linkage of KLF13 to oncogenesis was first reported in 2010 in oral squamous cell carcinoma, where it was reported to be tumor promoting." (PMID 38067370, 2023).
tumor (continued). "Similar questions are clear for tumor-associated pre-adipocytes and adipocytes and their corresponding KLF9 and KLF13 expression and actions." (PMID 38067370, 2023). "Experiments conducted in parallel confirmed the actions of specific miRs, lncRNAs, and circRNAs on KLF9 or KLF13 protein abundance and consequent effects on tumor cells in vitro and in vivo." (PMID 38067370, 2023). "We conclude that KLF13 exerts an anti-tumor effect by negatively regulating the expression of IFIT1 in THCA." (PMID 37817224, 2023). "We showed that KLF13 acted as an anti-tumor factor since it was downregulated in THCA samples and retarded the proliferation and migration of THCA cells." (PMID 37817224, 2023). "Meanwhile, the tumor weights of KLF13 groups were significantly smaller than those of control groups in both cell lines." (PMID 36336731, 2022). "These evidence indicate that KLF13 is versatile and it has multiple functions in regulating diverse physiology processes of non-neoplasia and tumor." (PMID 36336731, 2022). "Correspondingly, the clinical sample analysis indicated that KLF13 expression was correlated with PEBP1P2 expression in tumor tissues." (PMID 36348434, 2022). "In this paper, immunohistochemistry analysis uncovered that KLF13 was specifically and notably expressed in tissues of gastric pit while it was quite weak or even lost in tumor tissues." (PMID 36336731, 2022). "Statistically, the positive ratio of KLF13 expression in tumor tissues was only 13.79% while this ratio in normal tissues reached to 93.10%." (PMID 36336731, 2022). "Our study reveals that KLF13 acts as a tumor suppressor in CRC through negatively regulating HMGCS1-mediated cholesterol biosynthesis." (PMID 32523679, 2020). "In summary, we demonstrated that KLF13 served as a tumor suppressor in CRC through negatively regulating HMGCS1-mediated cholesterol biosynthesis." (PMID 32523679, 2020). "Overall, KLF13 overexpression obviously inhibited the xenografted tumor initiation and progression of HCT116 cells in vivo." (PMID 32523679, 2020). "Compare with control group, KLF13-knockdown group had lower tumor volume and weight." (PMID 40450000, 2025). "Given that its role in regulating drug metabolism pathways was entirely unknown, we prioritized KLF13 for in-depth investigation to determine if it represents a node connecting tumor suppression to chemosensitivity." (PMID 41438085, 2025). "Additionally, silencing of KLF13 raised the protein levels of SH2B1, IRS1, GLUT1, PDK1, and LDHA in xenograft tumours, and KLF13 overexpression exhibited the reverse actions." (PMID 41410190, 2025). "Furthermore, miR‐3126‐5p, SH2B1, and IRS1 levels were elevated, but KLF13 level was reduced in tumours of Exos‐treated mice, whereas KLF13 overexpression counteracted these changes, except change in miR‐3126‐5p expression." (PMID 41410190, 2025). "The results revealed that KLF13 knockdown suppressed EC cell proliferation, migration, epithelial-mesenchymal transition, increased cell apoptosis and cell cycle arrest in vivo and inhibited tumour growth in vitro." (PMID 40450000, 2025). "Our functional studies showed that KLF13 knockdown decreased cell viability, promoted apoptosis and induced cell cycle arrest of EC cells, thereby suppressing tumor growth, whereas KLF13 overexpression drove EC cell proliferation and migration, indicating a tumor promoter role for KLF13 in EC." (PMID 40450000, 2025). "Mounting evidence has proved the biological function of KLF13 in various tumours." (PMID 41410190, 2025). "Krüppel-like Factor-9 (KLF9) and Krüppel-like Factor-13 (KLF13) are highly related proteins that function as inducers and/or repressors of specific target gene repertoires in a variety of tissues and in diverse pathophysiological states, including neoplasia." (PMID 38067370, 2023). "Overexpression of KLF13 also suppressed tumor growth in vivo." (PMID 37817224, 2023).